SRPK1 (SRSF protein kinase 1)
Diseases named in the same sentence as SRPK1 in open-access papers (continued):
Sharing a sentence is not in itself a finding about the gene and the disease.
melanoma (11 papers, 2017 to 2025). A malignant, usually aggressive tumor composed of atypical, neoplastic melanocytes. "By using scRNA-Seq data, we verified that SRPK1/2 overexpression in malignant melanoma cells is linked to poor clinical outcomes." (PMID 36212152, 2022). "In conclusion, this study demonstrated SRPK1 dysregulation in melanoma patients using dataset analysis, both the transcript abundance and correlation with the patients’ survival." (PMID 41403742, 2025). "Inhibiting SRPK1 has been proved to have an antitumor effect in other cancer types, such as leukemia and melanoma." (PMID 36038837, 2022). "We evaluated the effect of SRPK1/2 genetic targeting on subcutaneous melanoma growth and development in mice." (PMID 36212152, 2022). "We previously demonstrated the anti-metastatic effect of pharmacological inhibitors targeting the SRPK1/2 family in melanoma." (PMID 36212152, 2022). "Considering the clinical correlations obtained from single-cell analysis, we approached a well-known murine metastatic melanoma model to better investigate the potential role of SRPK1/2 in vitro and in vivo." (PMID 36212152, 2022). "In melanoma cell lines, high SRPK1 expression favors angiogenesis through splicing regulation of a pro-angiogenic vascular endothelial growth factor (VEGF) isoform." (PMID 36212152, 2022). "Blocking the pro-angiogenic VEGF-Axxx isoform by inhibiting SRSF1 phosphorylation by SRPK1 inhibitors has been shown to reduce melanoma proliferation." (PMID 33807778, 2021). "In line with our observations, the inhibition of SRPK1 by SRPIN340 or trifluoromethyl arylamides maintained SRPK1 predominantly in the cytoplasm when melanoma cells were stimulated with EGF." (PMID 33808326, 2021). "It has been reported that blocking pro-angiogenic isoforms of VEGF, through inhibition of SRPK1, inhibits melanoma tumour growth in vivo." (PMID 33066024, 2020). "However, as SRPIN340 inhibits SRPK1 and to a lesser extent SRPK2, as well other splicing kinases, these data are limited in informing which SRPK1/2 member is relevant for melanoma progression." (PMID 36212152, 2022). "Three studies were identified, which explored the relationship between SRPK1 and melanoma." (PMID 35583632, 2022). "Interestingly, this cluster of malignant melanoma cells exhibited higher levels of SRPK2 than SRPK1." (PMID 36212152, 2022). "As selective SRPK pharmacological inhibitors are still unknown, the role of SRPK1 or SRPK2 activity in melanoma remains obscure." (PMID 36212152, 2022). "An oncogenic role of SRPK1/2 (Serine/arginine-protein kinase) was reported in various types of tumors, including leukemia and melanoma as well as pancreatic, breast, colon, lung, and ovarian cancer, hence different strategies have been proposed for the SRPK1/2 suppression." (PMID 32664456, 2020). "Finally, the more prominent impact of SRPK2 genetic targeting in impairing the development of murine melanoma in comparison to SRPK1 suggests that selective SRPK2 inhibition may be considered in further drug discovery efforts." (PMID 36212152, 2022). "Pan-SRPK inhibitor, SRPIN340 vs. SRPK1-specific inhibitor, and SPHINX31 were comparatively evaluated for their cellular effects in melanoma cells, A375 and MNT-1." (PMID 41403742, 2025). "To investigate the expression of SRPK1 and SRPK2 in human melanoma at single-cell resolution, we analyzed a dataset from human melanoma biopsies containing 6,696 cells identified by canonical lineage markers." (PMID 36212152, 2022). "So, our main objective in this work was to evaluate the possible differential roles of SRPK1 and SRPK2 in melanoma." (PMID 36212152, 2022). "This study aims to determine the clinical relevance of SRPK1 and SRPK2 expression regarding dataset analysis before examining the effects of SRPK inhibitors, SRPIN340 and SPHINX31, on cell viability and growth in the melanoma cell lines, A375 and MNT-1." (PMID 41403742, 2025).
melanoma (continued). "Consistently, genetic targeting of SRPK2, but not SRPK1, impaired the formation of pulmonary nodules and the development of subcutaneous melanoma in mice." (PMID 36212152, 2022). "As the used compounds could target at least both SRPK1 and SRPK2, here we sought to obtain additional clues regarding the involvement of these paralogs in melanoma progression." (PMID 36212152, 2022). "In further in vivo experiments, genetic targeting of SRPK2, but not SRPK1, reduced tumor progression in both subcutaneous and caudal vein melanoma induction models." (PMID 36212152, 2022). "The serine/arginine protein kinases 1 and 2 (SRPK1 and SRPK2) are classically related to the control of pre-mRNA splicing through SR protein phosphorylation and have been found overexpressed in many types of cancer, including melanoma." (PMID 36212152, 2022). "Furthermore, pro-angiogenic expression of VEGF-A in melanoma is activated by SRSF1, a pre-mRNA splicing factor, through phosphorylation of SRPK1." (PMID 33807778, 2021). "Although we cannot affirm that SRPK1 should promote melanoma progression (the differences were not significant), this hypothesis could not be discarded and should be better evaluated elsewhere." (PMID 36212152, 2022). "SRPIN340 preferentially inhibits SRPK1 and SRPK2, with a higher inhibitory effect on SRPK1, and was shown to reduce human melanoma tumor growth in vivo, but not in vitro, and was attributable to the regulation of VEGF expression and angiogenesis reduction." (PMID 35463320, 2022).
colon cancer (10 papers, 2008 to 2025). "Thus, our findings suggest that SRPK1 is significantly associated with colon cancer and might be a potential pharmaceutical target to treat colon cancer." (PMID 34193174, 2021). "On one hand, higher SRPK1 increased oxaliplatin-resistant of colon cancer cells, and knockdown of SRPK1 enhanced ovarian cancer sensitivity to cisplatin." (PMID 35192432, 2022). "SRPK1 was associated with clinical stage and TNM classifications in 148 cases of colon cancer patients." (PMID 34193174, 2021). "SRPK1 overexpression enhanced the anti-apoptosis ability of colon cancer cells, whereas SRPK1 silencing had the opposite effect under oxaliplatin treatment." (PMID 34193174, 2021). "We found that the levels of phosphorylated AKT, IKK, and IκB increased in SRPK1 overexpressing colon cancer cell lines, which contribute to the activation of the downstream NF-κB pathway." (PMID 34193174, 2021). "Collectively, these results indicated that elevated SRPK1 expression conferred an anti-apoptosis ability by activating the NF-κB pathway by increasing the phosphorylation of AKT in colon cancer." (PMID 34193174, 2021). "Taken together, we demonstrated that SRPK1 increased anti-apoptosis capacity in colon cancer cell lines." (PMID 34193174, 2021). "Taken together, in colon cancer, SRPK1 was increased at both the mRNA and protein levels, and SRPK1 was highly expressed over other different cancer types." (PMID 34193174, 2021). "Our finding suggested that SRPK1 enhances the anti-apoptosis ability of colon cancer via the NF-κB pathway by activating AKT." (PMID 34193174, 2021). "Together with the findings from xenografts, we concluded that PP1α can attenuates colon cancer progression at least partially via antagonizing SRPK1/2-induced SRSF1 phosphorylation and downstream MKNK2a-MKNK2b splicing shift." (PMID 33602301, 2021). "To determine the role of SRPK1 in colon cancer, we stably overexpressed or inhibited SRPK1 in SW480 and HCT-116 cells." (PMID 34193174, 2021). "Statistical analyses of IHC-stained sections showed that SRPK1 was overexpressed with increasing clinical stage of colon cancer." (PMID 34193174, 2021). "In the present study, we found that SRPK1 is overexpressed in tissues from patients with colon cancer and in colon cancer cells." (PMID 34193174, 2021). "Upregulation of SRPK1 expression increased the anti-apoptosis ability, whereas downregulation of SRPK1 expression increased the pro-apoptotic sensitivity of colon cancer cells." (PMID 34193174, 2021). "Overexpression of SRPK1 protein has been documented in acute type Adult T-cell leukemia, chronic myelogenous leukemia pancreatic, breast, and colon cancers." (PMID 23236423, 2012). "SRPK1 is up-regulated in breast and colonic tumors compared with adjacent normal epithelium, and the levels of the kinase increase along with tumor grade." (PMID 19516963, 2008). "Strong expression of SRPK1 protein was also evident in the majority of breast and colonic tumor cell lines." (PMID 19516963, 2008). "SRPK1 activity also appears to counteract apoptosis in colon cancer cells and might therefore be a general mechanism through which SRPK1 is involved in cancer, including AML." (PMID 36895328, 2023). "In addition, the phosphorylation of IKK and IκB were inhibited by an AKT inhibitor in SRPK1 overexpression colon cancer cell lines." (PMID 34193174, 2021). "Furthermore, we observed that and Bcl-xL levels increased, whereas Bcl-xS and cleaved PARP1 levels decreased, in SRPK1-overexpressing colon cancer cells, and the opposite effect was observed in SRPK1 knockdown cell lines." (PMID 34193174, 2021). "Taken together, we assumed that SRPK1 overexpression might increase AKT phosphorylation to induce NF-κB pathway activation to enhance the ability of anti-apoptosis in colon cancer cells against oxaliplatin treatment." (PMID 34193174, 2021). "The mRNA and protein levels of SRPK1 were increased in tissues from patients with colon cancer." (PMID 34193174, 2021).
colon cancer (continued). "Both the in vitro and in vivo data presented above suggested that elevated levels of SRPK1 might enhance anti-apoptosis in colon cancer cells." (PMID 34193174, 2021). "SRPK1 overexpression was significantly associated with clinical stage and the tumor-node-metastasis (TNM) classification of paraffin embedded sections from patients with colon cancer’." (PMID 34193174, 2021). "In conclusion, our findings suggested that SRPK1 might be a prognostic factor for survival, which is closely connect to treatment of patients with colon cancer." (PMID 34193174, 2021). "In addition, specific inhibition of SRPK1 might represent a potential anti-drug resistance therapy, and SRPK1 might also be a prognostic biomarker for oxaliplatin resistance in colon cancer." (PMID 34193174, 2021). "Our findings suggest that SRPK1 participates in colon cancer progression and enhances the anti-apoptosis capacity to induce drug resistance in colon cancer cells via NF-κB pathway activation, and thus might be a potential pharmaceutically target for colon cancer treatment." (PMID 34193174, 2021). "Thus, we speculated SRPK1 could be involved in colon cancer pathway activation by enhancing AKT phosphorylation." (PMID 34193174, 2021). "How SRPK1 mediates drug resistance in colon cancer is unknown." (PMID 34193174, 2021). "The changes in splicing fidelity elicited by SRPK1 down-regulation in breast and colon tumor cells have been shown to lead to production of aberrant MAP2K2 transcripts and protein, which in turn may reduce the availability of this kinase to phosphorylate its targets MAPK1/2." (PMID 23236423, 2012). "Taken together, these findings reveal that aberrant SRPK1 expression activates the NF-κB pathway via AKT, which participates in the anti-apoptosis process of colon cancer." (PMID 34193174, 2021). "The expression of SRPK1 was analyzed in the TCGA and the CPTAC pan-cancer samples and detected in colon cancer cell lines and tissues by IHC and western blot." (PMID 34193174, 2021). "Interestingly, interrogation of the cancer genome atlas (TCGA), found SRPK1 expression to be significantly lower in mucinous colon tumours compared to non-mucinous, with reduced expression correlating with reduced survival." (PMID 35583632, 2022).
colorectal cancer (10 papers, 2012 to 2023). A primary or metastatic malignant neoplasm that affects the colon or rectum. "SRPK1 is implicated in a host of signalling pathways known to drive oncogenesis in colorectal cancer." (PMID 35583632, 2022). "A previous study in colorectal cancer cells revealed that reducing SRPK1 levels by drug or siRNA treatment caused SRSF1 to be degraded in the cytoplasm." (PMID 32182205, 2020). "SRPK1 is implicated in other cancer types, including colorectal cancer and leukaemia." (PMID 36895328, 2023). "SRPK1 is a poor prognostic indicator in colorectal cancer in which it modulates SRSF1-mediated MKNK2 alternative splicing and is required for the expression of the cancer-associated splice variant RAC1B." (PMID 36895328, 2023). "SRPK1 silencing was found to inhibit proliferation, migration and invasion and increase rates of apoptosis of colorectal cancer cells across a number of included studies." (PMID 35583632, 2022). "miRNA-216b targets the 3’UTR of SRPK1 directly, and suppresses proliferation, migration and invasion in colorectal cancer cells, through SRPK1 inactivation." (PMID 35583632, 2022). "SRPK1 expression is responsible for preferential splicing of its oncogenic isoform in colorectal cancer cells, and its expression is regulated via the wingless/integrated (Wnt) signalling pathway." (PMID 35583632, 2022). "SRPK1 expression was generally found to be elevated in colorectal cancer, with the exception of the mucinous subtype." (PMID 35583632, 2022). "The over-expressed miR-216b restrained the cell proliferation, migration and invasion in HCC through the HBx-miRNA-216b-IGF2BP2 signaling pathway, a similar phenomenon was observed in colorectal cancer via targeting SRPK1." (PMID 34338136, 2021). "Similar to prostate and colorectal cancer, the SRPK1/SRSF1-driven VEGF alternative splicing also plays a key role in the regulation of angiogenesis in melanoma." (PMID 31861708, 2019). "Several oncogenic pathways and processes were reported to be deregulated after targeting SRPK1 in colorectal cancer." (PMID 31861708, 2019). "Promotes cellular proliferation, migration, and invasion via 1) binding to SFPQ and releasing oncogene PTBP2 from SFPQ/PTBP2 complex 2) increasing expression of AKAP-9 via promoting SRPK1-catalyzed SRSF1 phosphorylation in colorectal cancer cells." (PMID 27888635, 2017). "Thirteen studies explored the role of SRPK1 in colorectal cancer." (PMID 35583632, 2022). "SRPK1 inhibition increased the 4A/4B exon ratio in colorectal cancer cell lines." (PMID 31861708, 2019). "Other splicing factors shown to be over-expressed in colorectal cancer cells are hnRNP-F and –K, SPF45, and SRPK1." (PMID 22682314, 2012). "Similarly, GSK3β depletion in HT29 colorectal cancer cells led to a reduction in both SRSF1 and SRPK1 protein levels, suggesting an indirect effect of GSK3β on SRSF1 via SRPK1." (PMID 26273603, 2015).
pancreatic cancer (10 papers, 2012 to 2025). "We show that Endovion (SCO-101), a compound currently in clinical trials against pancreatic cancer, phenocopies the effects of the well-characterized SRPK1 inhibitor SRPIN340 on nascent transcription." (PMID 38775167, 2024). "SRPK1 silencing inhibits proliferation and induces apoptosis in pancreatic cancer cells, and enhances their sensitivity to gemcitabine and cisplatin treatment." (PMID 35583632, 2022). "When similar analyses were performed with breast, colonic, and pancreatic carcinoma lineages, the SRPK1 knockdown impacted the expression of MAP2K2 instead of MAP2K1, providing additional evidence for this different response according to each cell line." (PMID 26244849, 2015). "It has also been reported that the knock-down of SRPK1 in pancreatic carcinoma increases sensitivity to gemcitabine and cisplatin." (PMID 23071587, 2012). "Similarly, SRPK1 can control alternative splicing of MAP2K2 (a component of the MAPK pathway), where inhibition or knockdown of SRPK1 in pancreatic cancer cell lines led to increased sensitivity to chemotherapy agents." (PMID 37607329, 2023). "A single study explored the role of SRPK1 in pancreatic cancer." (PMID 35583632, 2022).
non-small cell lung carcinoma (9 papers, 2012 to 2024). A group of at least three distinct histological types of lung cancer, including non-small cell squamous cell carcinoma, adenocarcinoma, and large cell carcinoma. "SRPK1 expression is elevated in Non Small Cell Lung Cancer (NSCLC) tissue and is associated with increased growth and migration in NSCLC cells." (PMID 35583632, 2022). "Additionally, the expression of SRPK1 is correlated with the expression of EGFR in non-small-cell lung cancer patients, and the overexpression of SRPK1 is associated with EGFR (epidermal growth factor receptor) expression." (PMID 38397980, 2024). "Downregulation of SRPK2 in non-small cell lung cancer cells prevented the induction of apoptosis following cisplatin treatment, whereas downregulation of SRPK1 increased apoptosis." (PMID 33808326, 2021). "Up-regulation of SRPK1 in non-small cell lung cancer promotes the growth and migration of cancer cells." (PMID 31992202, 2020). "Besides small-molecule inhibitors, chimeric antibody targeting SRPK1 also inhibits non-small cell lung cancer progression on multiple aspects." (PMID 35192432, 2022). "SRPK1 overexpression can also induce stem cell-like phenotype in non-small-cell lung carcinoma." (PMID 35192432, 2022). "Immunohistochemical analysis of SRPK1 and SRPK2 proteins expression in non-small cell lung cancer according to histological subtype." (PMID 23071587, 2012). "Except its reported overexpression in non-small cell lung cancer (NSCLC) compared to normal lung tissue, evidence shows that SRPK1 expression status could be a prognostic factor in this cancer type." (PMID 31861708, 2019).